LY6G5B (lymphocyte antigen 6 family member G5B)
Synonyms: C6orf19; G5B
Tractability: Antibody: UniProt places it where antibodies can reach, with high confidence; UniProt predicts a signal peptide or a membrane-spanning region; its Gene Ontology location is reachable by antibodies, with medium confidence.
Gene: Protein-coding gene on chromosome 6 (31,669,976 to 31,673,776, forward strand). Ensembl gene ENSG00000240053.
Subcellular location: Secreted
Gene Ontology:
Molecular function: identical protein binding
Cellular component: external side of plasma membrane; protein-containing complex; extracellular region
Genetic constraint (gnomAD): Loss-of-function variants: 6 observed, 6.96 expected, observed/expected ratio (o/e) 0.86, 90% interval 0.47 to 1.64. That is too few expected variants to judge how well the gene tolerates losing a copy. Missense variants: 240 observed, 262.93 expected, observed/expected ratio (o/e) 0.91, 90% interval 0.82 to 1.02. Synonymous variants: 98 observed, 103.88 expected, observed/expected ratio (o/e) 0.94, 90% interval 0.8 to 1.12.
Homologues: Orthologues: chimpanzee CSNK2B (87% identical), macaque CSNK2B (82% identical), dog LY6G5B (74% identical), rabbit LY6G5B (74% identical), pig LY6G5B (72% identical), guinea pig LY6G5B (67% identical), rat Ly6g5b (62% identical), mouse Ly6g5b (61% identical).
Diseases named in the same sentence as LY6G5B in open-access papers:
LY6G5B is named in the same sentence as 6 diseases in open-access papers, as found by Europe PMC text mining. Sharing a sentence is not in itself a finding about the gene and the disease. The quoted sentences say what the papers report.
Infertility (1 paper, 2024). "In this study, we took advantage of the CRISPR/Cas9 system by knocking out the epididymis-enriched Lcn8/5/6/10/9 and Ly6g5b/c gene clusters and found infertility phenotypes." (PMID 36428102, 2024).
rheumatoid arthritis (1 paper, 2021). A chronic, systemic autoimmune disorder characterized by inflammation in the synovial membranes and articular surfaces. "Among these novel identified genes, several genes (e.g., LY6G5B and DDAH2) were associated with autoimmune-related diseases, including rheumatoid arthritis and type 1 diabetes." (PMID 34872583, 2021).
LY6G5B also shares sentences with these, for which no sentence is quoted: autosomal recessive spastic paraplegia-86 (1 paper); Spastic paraplegia (1); tumor (1); type 1 diabetes (1).